SRC (SRC proto-oncogene, non-receptor tyrosine kinase)
Diseases named in the same sentence as SRC in open-access papers (continued):
Sharing a sentence is not in itself a finding about the gene and the disease.
breast cancer (continued). "SRC-3f/f:Foxp3Cre-ERT2/+ and SRC-3f/f female mice were first injected with E0771:LUC breast cancer cells." (PMID 37253006, 2023). "However, the mechanisms underlying the overexpression of SRC in breast cancer still remain unclear." (PMID 37439249, 2023). "Growing evidence has unraveled that oncogenic overexpression or dysregulated activation of SRC drives breast cancer development and progression." (PMID 37893115, 2023). "TLK2 enhances the aggressiveness of breast cancer through the activation of the EGFR/SRC/FAK signaling pathway." (PMID 38343446, 2023). "In accordance with our observation, previous studies also reported upregulation of SRC activities in breast cancer tissues compared to normal breast tissues." (PMID 35273218, 2022). "SRC regulates cell migration and invasion in breast cancer metastasis by stimulating the FAK/SRC/Rac1 signaling pathway." (PMID 35062973, 2022). "Overall, these data indicate that: CCL2 triggers interactions among CCR2, MET and SRC in breast cancer cells, and CCL2 regulates MET phosphorylation through CCR2- and SRC-dependent mechanisms." (PMID 35405500, 2022). "The primary tumor was also tested through IHC, NP‐C8018‐7840 significantly inhibited the phosphorylation of PTK2B at Tyr402, PTK at Tyr397, and SRC at Tyr416 of the breast cancer primary site, but had little impact on total‐PTK2B, total‐PTK, and total‐SRC." (PMID 36285700, 2022). "Of particular relevance is the stimulation of the IGF1 receptor (IGF1R) which was found to form a heterotrimeric complex with HER2 and HER3 resulting in SRC activation in breast cancer cells." (PMID 36466034, 2022). "Asiatic acid induced HT-29 cell apoptosis via CASP3 activation and inhibited the growth and metastasis of breast cancer in mice by downregulating SRC protein expression." (PMID 36437827, 2022). "The SRC oncogene is also involved in various tumor signaling pathways, and is often abundantly expressed in breast cancer." (PMID 36276152, 2022). "PTPN13 can dephosphorylate ERK and AKT in tumor cells and inhibit breast cancer by directly dephosphorylating SRC." (PMID 36096985, 2022). "PRKAR1A is associated with poor patient prognosis in basal‐like breast cancer, and low PRKAR1A/high SRC expression has been linked to basal‐like and HER2+ breast cancers with adverse clinical outcome." (PMID 35000262, 2022). "SRC is overexpressed or highly active in various solid tumor cell lines and tissues, and SRC inhibitors abrogate breast cancer cell invasion and metastasis." (PMID 35296801, 2022). "To test this, we studied SRC–FAK binding in breast cancer MDA-MB-231 cells by coimmunoprecipitation after treatment with eCF506 and clinical kinase inhibitors dasatinib, bosutinib, and saracatinib." (PMID 34417202, 2021). "SRC recruitment is essential for PyMT mediated signaling and transformation as full-body knockout of c-Src rendered PyMT incapable of generating mammary tumors." (PMID 33235291, 2021). "Encouraged by the distinct mechanism of action and increased selectivity of eCF506, we screened eCF506 and clinical SRC/ABL inhibitors against a panel of 16 breast cancer cell lines." (PMID 34417202, 2021). "Overexpression or hyper-activation of the HER/SRC tyrosine receptor kinase family is known to contribute to endocrine resistance in breast cancer." (PMID 32771039, 2020). "It was shown that the continuously activation of Stat3 related with the aberrant activation of JAK and c-SRC in breast cancer cells, and inhibition of Src damaged the activity of Stat3 DNA-binding." (PMID 32565740, 2020). "SRC is broadly overexpressed in luminal breast cancer and can crosstalk with HER2 when facilitated by other molecules such as CDCP1." (PMID 32771039, 2020). "It controls cortactin phosphorylation in a SRC/ARG-dependent manner in breast cancer cell line MDA-MB-231 and other tumor cells." (PMID 31052560, 2019).
breast cancer (continued). "Recently, it was also shown that SRC phosphorylation of ETS-1 at tyrosine 283 released COP1 degradation of ETS-1 in breast cancer." (PMID 31118072, 2019). "In summary, we show that SRC is critical for YAP/TAZ activity in many breast cancer and melanoma cell lines and that SRC-mediated activation of YAP and TAZ plays important roles in tumor growth and metastasis." (PMID 30559289, 2019). "We built gene interaction network for 30 targets associated with breast cancer and observed ER1, EGFR, and SRC were the strongest effector for the relationship." (PMID 30906412, 2019). "Consistent with these latter studies, we found that in breast cancer and melanoma cells, SRC can promote YAP/TAZ activity by repressing LATS (our findings)." (PMID 30559289, 2019). "Investigations indicate that SRC is up-regulated in various cancers such as brain, colon, pancreas, and breast cancers." (PMID 31191840, 2019). "This integrin was observed in adhesion ring of breast cancer cell lines, and in the invadopodia puncta when cells present activated SRC." (PMID 31052560, 2019). "Less attention has been paid to the levels of SRC, despite that the upregulation of its stability and synthesis promotes breast cancer metastasis." (PMID 30764849, 2019). "Nevertheless, our data show that SRC is essential to maintain YAP/TAZ activity in many breast cancer and melanoma cells and that elevated SRC-mediated YAP/TAZ activity is required for metastasis." (PMID 30559289, 2019). "Here we demonstrate that SRC is an important driver of YAP/TAZ activity in several breast cancer and melanoma cell lines and show that SRC-mediated YAP/TAZ activation is important for tumor growth and metastasis." (PMID 30559289, 2019). "In breast cancer cells, THs regulate cell migration via integrin αvβ3 that activates SRC/FAK/PI3-K pathway." (PMID 30814977, 2019). "In this study, we have provided evidence that SUMOylated PYK2 enhances motility of MDA-MB-231 metastatic breast cancer cells via signaling through the SRC, paxillin, and ERK1/2 signaling cascade." (PMID 29438996, 2018). "It has also been demonstrated that SRC regulates breast cancer cell proliferation and invasion through the autocrine/paracrine activity of SDF-1α/CXCL12." (PMID 30103827, 2018). "Among the candidate target genes, PTEN was the potential target for miR-940, IGF1R for miR-451a and miR-16-5p, and SRC for miR-17-3p, as aberrant signaling of PTEN, IGF1R, and SRC has been involved in trastuzumab resistance of breast cancer cells." (PMID 29691399, 2018). "The most widely studied steroid receptor coactivator family in breast cancer are the p160 kDa group of SRC −1 (NCOA1), −2(NCOA2), and −3 (NCOA3/AIB1)." (PMID 30416486, 2018). "As SRC plays an important role in breast cancer progression and several SRC inhibitors are already being tested in breast cancer clinical trials, we used SRC inhibitors to further assess its SL properties." (PMID 27418135, 2016). "Breast cancer cell migration and invasion were also inhibited by sortilin knockdown, with a decrease in focal adhesion kinase and SRC phosphorylation." (PMID 25871389, 2015). "In support of this, we observed that c-MYC and c-SRC, proteins elevated in breast cancers, were also elevated following TFPI1 expression." (PMID 24489651, 2014). "Notwithstanding, our analysis indicates that ERK8 is frequently downregulated in lung and breast carcinomas, which probably facilitates the relocation of GalNac-Ts to the ER when other biochemical or genetic perturbations, such as SRC activation, are engaged." (PMID 24618899, 2014). "Molecular studies of each SRC in MCF-7 breast cancer cell suggest that the SRCs exhibit differential regulation of endogenous ER-target genes, indicating specific contributions of each SRC member to promote breast cancer." (PMID 23936147, 2013). "SRC is able to repress miR-126 expression levels and furthermore miR-126 has been described as a suppressor of proliferation and metastasis in breast cancer." (PMID 22384141, 2012).
breast cancer (continued). "Because we profiled CSF-1R-induced and SRC-dependent changes in tyrosine phosphorylation in a mammary epithelial cell line, we first analyzed a small breast cancer dataset, derived from only eight tumors, available publicly from CST's PhosphoSitePlus®." (PMID 21049007, 2010). "Additionally, studies in breast cancer revealed SRC as a common node downstream of multiple resistance pathways." (PMID 40481178, 2025). "In breast cancer cells, SRC-driven PI3K/AKT activation is a critical driver of cell apoptosis." (PMID 41017855, 2025). "However, CP has previously been shown to increase migration and invasion of breast cancer cells through c-SRC pathway activation, amplifying downstream AKT and p-38 signaling." (PMID 37624215, 2023). "In breast cancer cells, P-cad is also known to promote cell motility, collective cell migration and invasive capacities by potentiating the activation of the SRC proto-oncogene and by signaling through SRC and α6β4 integrins." (PMID 36808468, 2023). "SRC overexpression was first observed over two decades ago in human breast cancer." (PMID 37439249, 2023). "SPRY2 has been reported to interact with SRC and SRC could phosphorylate LDHA at tyrosine 10 in breast cancer." (PMID 37507768, 2023). "In addition, SRC is also a common cancer-promoting pathway, and it can promote the occurrence of breast cancer by inducing mitochondrial dysfunction." (PMID 36755247, 2023). "Additionally, The Cancer Genome Atlas (TCGA) database analysis revealed that SRC is significantly overexpressed in human breast cancers." (PMID 37439249, 2023). "The study reported that SRC modulates the antibody Trastuzumab that targets the human epithermal growth factor receptor-2 (HER-2 or ERBB2) response in breast cancer, and that activating SRC by phosphorylation at Tyr416 was required for regulating the multiple resistance pathways." (PMID 35954330, 2022). "Besides, another study established that leptin elevates the expression levels of Twist and β-catenin, as well as the release of invasion markers MMP-2 and MMP-9 in breast cancer cells, leading to enhanced cell invasion in an SRC- and FAK-dependent way." (PMID 35379785, 2022). "Additionally, we tested the ability of AZD0424 to inhibit SRC activation and tumour growth of one of the sensitive breast cancer cell lines in vivo." (PMID 34856074, 2022). "In addition, Liu inhibited the progression of estrogen receptor-positive breast cancer by constructing MiR-4458-loaded gelatin nanospheres targeting COL11A1 to block the DDR2/SRC signaling pathway." (PMID 36160004, 2022). "Furthermore, PTK6 and SRC activation have been correlated with resistance to HER2 inhibitors in breast cancer." (PMID 36228719, 2022). "Moreover, there is a relationship between the SRC and estrogen receptor, which makes the SRC a novel source of investigation in response to therapy in tumors like breast cancer." (PMID 35290401, 2022). "In addition, the gene-disease analysis showed that three out of four hub genes (CXCL2, SRC and SPP1) were also associated with mammary neoplasms, pulmonary fibrosis, dermatitis and allergic contact diseases." (PMID 35452485, 2022). "Additionally, the protein-disease interaction networks showed three out of five hub genes (CXCL2, SRC and SPP1) are also associated with mammary neoplasms, pulmonary fibrosis, dermatitis and allergic contact diseases." (PMID 35452485, 2022). "Importantly, the antiproliferative potency of eCF506 in the sensitive breast cancer cells correlated well with the observed inhibition of SRC-pY419, although the potential contribution of partly inhibiting other targets (e.g., BRK) cannot be ruled out." (PMID 34417202, 2021). "PP-2, an inhibitor of SRC, may significantly ameliorate the invasiveness of breast cancer cells and enhance the radiosensitivity of glioma cells." (PMID 33712015, 2021).
breast cancer (continued). "Indeed, eAGR3 regulates breast cancer cell migration via SRC signalling, and thus promotes the proliferative and invasive abilities of breast cancer cells." (PMID 34452625, 2021). "ESR1-CCDC170 may endow breast cancer cell survival under endocrine therapy via maintaining/activating HER2/HER3/SRC/AKT signaling which implies a potential therapeutic strategy for managing these fusion positive tumors." (PMID 32771039, 2020). "While SRC has been reported to play a key role in breast cancer bone metastasis and hormonal therapy resistance, the clinical trials of SRC inhibitors in unselected metastatic breast cancer patients have been disappointing." (PMID 32771039, 2020). "Here, we provide detailed evidence supporting the function of ESR1-CCDC170 in endowing breast cancer cell survival and reducing endocrine sensitivity in vitro and in vivo and unravel its novel action mechanism via modulating and activating the SRC/HER2/HER3 complex." (PMID 32771039, 2020). "The possible mechanisms might be that RA inhibited the SRC/AKT signaling pathway in osteoclasts as well as AKT/mTOR signaling in breast cancer cells." (PMID 29515110, 2018). "Additionally, in all four GPR30-positive breast cancer lines, calycosin decreased the phosphorylation levels of SRC, EGFR, ERK1/2 and Akt, but the inhibition of WDR7-7 blocked these changes and increased proliferation." (PMID 29096683, 2017). "As SRC inhibitors are being actively evaluated in breast cancer clinical trials, our findings strongly suggested that the SL interaction between EPHB6 and SRC might be used to target TNBC tumors." (PMID 27418135, 2016). "Therefore, the sortilin knockdown-induced inhibition of MDA-MB-231 breast cancer cell invasion involves a decrease in SRC/FAK signaling pathways." (PMID 25871389, 2015). "Overexpression and functional activation of FAK, moesin, and c-SRC in breast cancer cells may in part explain this epidemiologic finding." (PMID 26733941, 2015). "In breast cancer cells, MET and SRC cooperate to compensate for the loss of EGFR TKI activity." (PMID 24714091, 2014). "SRC-3 is another member of the SRC gene family, which is specifically amplified in breast cancer." (PMID 21080969, 2010). "Previous studies have shown that basal-type and post-EMT breast cancer cell lines are particularly sensitive to dasatinib, with elevated expression of genes such as moesin (MSN), caveolin-1 (CAV1), and yes-associated protein-1 (YAP1), which are associated with the SRC signaling pathway." (PMID 41462902, 2025). "SRC might be one of the key targets of Tamarixetin in mitigating breast cancer progression." (PMID 35273218, 2022). "In addition, SRC inhibitors have been shown in preclinical trials that they may be used in targeted therapy for advanced breast cancer by inhibiting bone metastasis." (PMID 33830879, 2021). "VE-cadherin effects on proliferation of metastatic mammary cancer cells, which were previously attributed to the TGFβ pathway, could also be explained with the outside-in α2β1 integrin activation and the subsequent activation of the SRC, ERK and JNK pathways." (PMID 27966446, 2017). "Moreover, SRC may associate with HER receptors, and previous data in HER2‐overexpressing breast cancer cells indicated that SRC inhibition prevented ERK1/2 activation." (PMID 29032615, 2017). "Furthermore, we found that TLK2 may involve the EGFR/SRC/FAK axis to enhance breast cancer cell invasiveness." (PMID 27694828, 2016). "However, the relevance of these targets in human tumors is not clear, as SRC is not frequently mutated or overexpressed in breast cancers, and it is more likely activated in breast carcinomas by an upstream activated RTK or another receptor known to couple to SRC." (PMID 21049007, 2010). "In breast cancer, the Top 5 genes were MYC, EGFR, SRC, HSP90AB1, PXDNL, and the Top 4 genes are CGC drivers." (PMID 40478912, 2025).
breast cancer (continued). "Specifically, in breast cancer (BRCA) and head and neck squamous cell carcinoma (HNSC), PRKN, PINK1, and MAP1LC3A were downregulated, while SRC and BECN1 were upregulated." (PMID 39859167, 2025). "Previously, we have reported that TGBR2, PI3K, SRC, FAK, and HIF1-α were direct targets of miR-204 in breast cancer cells." (PMID 38392969, 2024). "For instance, CCL2 has been reported to promote proliferation and cell cycle progression by activating SRC and PKC in basal-like breast cancer cell lines." (PMID 38167009, 2024). "A recent study has shown that CBD can inhibit breast cancer growth by inhibiting SRC activity, thereby upregulating VHL expression, reducing HIF-1α synthesis in breast cancer cells, and inhibiting angiogenesis." (PMID 38731434, 2024). "SRC/GSTP1 expression and G6PDY249/322 phosphorylation were positively correlated in breast cancer tissues characterized to be ER (+) and PR (+) or HER (-); however, this correlation was not evident in ER(-)/PR(-) or ER(-)/PR(+) or HER (+) tumor tissues." (PMID 37491277, 2023). "In breast cancer cells, lactate dehydrogenase (LDH) has been found to be phosphorylated and thus activated by HER2 and SRC, and that the inhibition of such phosphorylation is associated with decreased invasiveness." (PMID 36945054, 2023). "Further, the IP-enriched SRC/GSTP1 protein and G6PDY249/322 Tyr phosphorylation status were strongly and positively correlated with the breast cancer that exhibit ER expression and PR expression, to which our experimental cell line MCF-7 belongs." (PMID 37491277, 2023). "Tyrosine 40 in the LIR domain of paxillin is a target of SRC kinase; SRC increases the LC3B–paxillin interaction and promotes the migration of breast cancer cells." (PMID 36831154, 2023). "In addition, PFKFB4 could phosphorylate SRC to promote the progression of breast cancer and LUAD." (PMID 37500615, 2023). "HPSE was previously reported to promote tumor growth and metastasis in breast cancer by modulating phosphorylation of AKT, STAT5, and SRC." (PMID 36130926, 2022). "At the same time, in HER2-positive breast cancer, NCAPG promotes the development of trastuzumab resistance by activating the SRC/STAT3 axis." (PMID 35254214, 2022). "By a knockdown of Gal-1 in breast cancer, the Gal-1/integrin β1 interactions have been highlighted because the depletion of Gal-1 negatively impacts the signaling pathway downstream of FAK/SRC." (PMID 34063063, 2021). "In agreement with the literature, our results indicate that SRC activity has a minor role on the proliferation and survival of HER2-driven breast cancer cell lines, but it can become a driver of resistance in the context of HER2 inhibition." (PMID 34417202, 2021). "Low PRKAR1A/high SRC mRNA has been shown to define basal‐like and HER2‐positive breast cancers with a worse clinical outcome, and PKA activity has also been implicated in HER2 resistance in vitro, in particular down‐regulation of the PKA‐RIIα subunit." (PMID 33991172, 2021). "HER2/HER3 heterodimer functions as a major oncogenic unit and is known to crosstalk with SRC and activates PI3K/AKT pathway to drive breast cancer." (PMID 32771039, 2020). "The sensitivity of ESR1-CCDC170 expressing breast cancer cells to concomitant treatments of tamoxifen and HER/SRC inhibitors was assessed by clonogenic assays." (PMID 32771039, 2020). "Our results also imply a potential therapeutic strategy to manage ESR1-CCDC170-positive breast cancer patients via combining HER2 and/or SRC inhibitors with endocrine therapy." (PMID 32771039, 2020). "In breast cancer cells, TNC induces EMT by activation of SRC proto-oncogene tyrosine kinase (SRC) through phosphorylation at Y418 and through phosphorylation of focal adhesion kinase (FAK) at SRC substrate sites Y861 and Y925." (PMID 32252322, 2020).